CDK1 (cyclin dependent kinase 1)
Diseases named in the same sentence as CDK1 in open-access papers (continued):
Sharing a sentence is not in itself a finding about the gene and the disease.
lung cancer (continued). "CDK1 can also interact with Sox2 to increase the stemness of lung cancer cells." (PMID 38189879, 2024). "CDK1 positively regulated the lung cancer cell’s stemness via interacting with Sox2." (PMID 37689745, 2023). "Based on the results of this study, we speculate that CDK1 has excellent value in the survival and prognosis of lung cancer patients and may provide some possibilities for targeted drug delivery of lung cancer chemotherapy." (PMID 36714024, 2023). "CDK1 levels decreased significantly in both lung cancer cell types." (PMID 37759783, 2023). "Indeed, among the several cell cycle‐related proteins investigated, CyclinB1 and CDK1 were noticeably decreased upon VLX1570 treatment in a dose‐dependent manner in lung cancer cells." (PMID 34854221, 2022). "Furthermore, this study found that the expression of other lung cancer-related factors CDK1, CDC20, P38α and CUEDC were all significantly increased in the left lung of stress+smoke mice when compared to the each single group." (PMID 36417428, 2022). "In addition, CDK1 mRNA expression was negatively correlated with the overall survival of lung cancer patients, and CDK1/Sox2 regulated the activity of liver cancer stem cells in a positively regulated manner." (PMID 36339610, 2022). "Moreover, mechanistic study clarifies that the regulation of lung cancer by NLE1 needs the participation of CDK1 as a downstream target, whose E2F1-mediated transcription was regulated by NLE1." (PMID 36818671, 2022). "CDK1 was upregulated in lung cancer, and it acts as a potential prognostic biomarker." (PMID 36268280, 2022). "In addition, dinaciclib was shown to trigger abnormal mitotic division (anaphase catastrophe) in lung cancer cells through, CDK1 and CDK2 suppression." (PMID 33777535, 2021). "CDK1 serves as a prognostic biomarker for cancers including colorectal and lung cancers." (PMID 33742334, 2021). "Moreover, high mRNA expression of CDK-1 is linked to poor OS in CRC, hepatocellular carcinoma and lung cancer." (PMID 33732631, 2021). "Lung cancer patients with high expression of CDK1 have worse overall survival." (PMID 34586751, 2021). "Many studies reported the important role of CDK1 in the malignancy of lung cancer." (PMID 34307447, 2021). "CENPA and CDK1 were also identified as prognostic markers of lung cancer." (PMID 35223866, 2021). "In addition, a previous study reported that CCNA2, CDC20, PBK, and TOP2A that interacted with CDK1 play vital roles in survival outcomes in human lung cancer." (PMID 32426332, 2020). "In addition, silencing of miR-21 in A549 human lung cancer cells increased oxidative damage and the cell cycle was blocked at the G0/G1 phase by downregulation of CDK1, thus reversing multidrug resistance of lung cancer cells." (PMID 35006436, 2020). "CDK1 overexpression has been documented in lung cancer, lymphoma, and advanced melanoma." (PMID 33014840, 2020). "Our results may contribute to the development of potential strategies to target GP130/STAT3 signaling and suppress lung cancer via CDK1 blockade and iron deprivation." (PMID 30931929, 2019). "Moreover, CDK1/GP130/STAT3 signaling were elevated in lung cancer tissues compared with adjacent normal lung tissues." (PMID 30931929, 2019). "However, the molecular mechanisms and potential applications of CDK1 in lung cancer remain undetermined." (PMID 30931929, 2019). "However, the molecular mechanism and the potential applications of CDK1 with respect to lung cancer are yet unclear." (PMID 30931929, 2019). "Therefore, we examined the relationships between BEX4 expression and PLK1 and CDK1 expression in human lung cancer cells." (PMID 30367032, 2018).
lung cancer (continued). "For another member of the PLK family, PLK4, was demonstrated that haploinsufficient Plk4 + /- mice have a higher incidence of liver and lung cancer, which was due to an impaired regulation of Cyclins D1, E and B1 and of CDK1 supporting a critical role of polo-like kinases for tissue homeostasis." (PMID 29549256, 2018). "CDK1 expression was shown to be up-regulated in lymphoma, advanced melanoma and lung cancer." (PMID 30020984, 2018). "Furthermore, active Cdk1 facilitates the smooth transition of lung cancer cells from the G2 phase to the M phase, and promotes cell growth and proliferation." (PMID 25663895, 2015). "Our study is the first to combine PVT1 and miR-143–3p within a ceRNA axis that converges on CDK1, offering a systems-level viewpoint that unifies non-coding RNA regulation with a central cell cycle kinase, even though both have been previously connected to lung cancer." (PMID 41080754, 2025). "In addition, SOX2 interacts with CDK1 to promote lung cancer cell stemness." (PMID 38164286, 2024). "In addition, the aberrant upregulation of CDK1 is also detected in lung cancer and colorectal cancer and positively correlated with pathological stage and lymphatic metastasis, although its exact substrates and the detailed mechanism remain not fully understood." (PMID 36813923, 2023). "Besides, numerous studies have demonstrated the critical role of CDK1 in the development and drug resistance in lung cancer, which could act as prognostic biomarker and therapeutic target." (PMID 36818671, 2022). "When lung cancer cells were treated with a nano‐emulsion of curcumin extract, it was found that H460 cells were more prone to apoptosis than A549 cells and that the cell cycle remained in the G2/M phase, accompanied by a dose‐dependent decrease in CDK1 expression." (PMID 33650320, 2021). "In addition, CDK1 also was regarded as a potential prognostic biomarker in lung cancer." (PMID 34950739, 2021). "Another cell cycle regulator, cyclin‐dependent kinase 1 (CDK1), was also involved in the progression of multiple types of cancer, including colorectal cancer, liver cancer, and lung cancer." (PMID 41541703, 2026). "For instance, in colon and lung cancer cell lines, STAT3 is upregulated by iron-dependent activation of cyclin-dependent kinase 1, and it promotes the expression of GPX4, a key regulator of ferroptosis resistance." (PMID 40867343, 2025). "CDK1 can interact with the stemness marker SOX2 protein and positively regulate the stemness of lung cancer cells." (PMID 38577615, 2024). "Therefore, CHEK1, CCNB1, CCNB2, and CDK1 may be helpful prognostic biomarkers for lung cancer." (PMID 36714024, 2023). "The average protein abundances among representative lung cancer proteins, EGFR, CDK1, and MAP2K1, revealed good linearity between the measured protein abundance and increasing cell numbers." (PMID 35013269, 2022). "Compared to primary lung cancer, all the expression of hub genes increased in lymph node metastasis samples, and the expression of BUB1, BUB1B, CDK1, CCNA2 and CDC20 were related to peritoneum metastasis." (PMID 36176446, 2022). "Further screening by establishing gene co-expression networks and preforming prognostic analysis identified CDK1, CCNB2, and CDC25A as the hub genes involved in lung cancer carcinogenesis and development." (PMID 34446056, 2021). "Altogether, the present results suggest that CDK1 inhibition and iron deprivation are potential strategies to target GP130/STAT3 signaling to suppress lung cancer." (PMID 30931929, 2019). "CDK1, GP130, and p-STAT3 were upregulated in lung cancer tissues compared with adjacent normal lung tissues." (PMID 30931929, 2019). "To further investigate the clinical relevance of our findings, we performed immunohistochemical staining to assess the CDK1, GP130, and p-STAT3 expression in lung cancer tissues and adjacent normal lung tissues." (PMID 30931929, 2019).
lung cancer (continued). "Immunoblotting analysis revealed that PLK1 was overexpressed in 10 of the 11 lung cancer cells, and unexpectedly, 9 of the lung cancer cell lines showed a significant positive correlation between the expression of BEX4 and the expression of PLK1 or CDK1." (PMID 30367032, 2018). "We determined the CDK1, CDK4 and CDK6 mRNA expression alterations due to transfection with miR-143 and/or miR-506 in A549 lung cancer cells using quantitative real-time PCR (qRT-PCR)." (PMID 30002440, 2018). "Further intersecting these predicted targets with transcriptomic datasets from breast, colorectal, and lung cancers highlighted hub proteins such as TYMS, AURKA, CDK1, and TK-1, which are critical regulators of DNA synthesis, mitotic progression, and cell cycle checkpoints." (PMID 40430485, 2025). "Notably, indomethacin induced SSAT-1 expression via the nucleolin-CDK1 axis and exhibited synergistic anticancer effects with the PAOX inhibitor methoctramine in lung cancer cells." (PMID 40813717, 2025). "In addition, CENP-A, together with CDK1 (Cyclin-dependent kinase 1) and CDC20 (Cell division cycle protein 20), are found to be highly co-expressed in lung cancer tissues." (PMID 39273649, 2024). "In addition, we also found that PLK1, CDK1, CCNB1, and CCNB2 were upregulated in lung cancer, liver cancer, and cervix cancer tissues from HPA." (PMID 37007025, 2023). "A bioinformatics study revealed that CDK1 stimulates the stemness of lung cancer cells by the interaction with SOX2 and that increased CDK1 expression shows relationship to lower overall survival in patients suffering from lung cancer." (PMID 37808164, 2023). "In our future work, whether NLE1 regulates lung cancer through Notch1 signaling and the molecular regulatory mechanism between NLE1 and CDK1 would be further explored and investigated." (PMID 36818671, 2022). "It was found that TOP2A, CCNB1, CCNA2, CDK1, and TTK might be the critical target genes of lung cancer." (PMID 34616430, 2021). "Moreover, up-regulation of AURKA/PLK/CDK1 contributes to PI3K inhibitor resistance in glioblastoma, and AURKA drives the evolution of resistance to EGFR inhibitor in lung cancer." (PMID 34359608, 2021). "In the transcriptome of our EVs, we found also MIR490 that seems to have the role of tumor suppressor in lung cancer cells A549 and ovarian cancer by blocking the transcription of CCND1 and CDK1 respectively, two important genes involved in cell cycle progression." (PMID 32582296, 2020). "CDK1 and STAT3 are essential for iron-mediated colony formation in lung cancer cell lines." (PMID 30931929, 2019). "As shown, several well‐known oncogenes were co‐expressed with circRNA, such as Wnt3A, CDK1, and BUB1, indicating these circRNA might participate in the pathological process of lung cancer." (PMID 29632808, 2018). "TOP2A, CCNB1, CCNA2, CDK1, and TTK may be the key target genes of lung cancer." (PMID 34616430, 2021). "However, the molecular mechanism and potential application of CDK1 in lung cancer have not been determined." (PMID 33178836, 2020). "The treatment of A549 cells with Mito-TEMPO significantly reversed both the ABN-B-induced up-regulation of p21 and the down-regulations of cyclin B1 and CDK1, suggesting that ABN-B could induce cell cycle arrest at the G2/M phase in human lung cancer cells via mitochondrial ROS generation." (PMID 33327489, 2020). "IRF1 is downregulated in lung cancer, IPF and PAH datasets, probably because it represses the expression of genes involved in anti-proliferative response, such as BIRC5/survivin, CCNB1, CCNE1, CDK1, CDK2 and CDK4 and in immune response, such as FOXP3, IL4, ANXA2 and TLR4." (PMID 31867044, 2019).
lung cancer (continued). "In addition, inhibition of CDK2, but not CDK1, induced growth arrest in lung cancer cell lines through anaphase catastrophe." (PMID 25301183, 2014). "In this study, except for the regulatory effects of CDK1 itself, we also found that knockdown of CDK1 could partially eliminate the promotion effects of lung cancer induced by NLE1 overexpression, suggesting CDK1 as an essential link in the function of NLE1 in lung cancer." (PMID 36818671, 2022). "In the context of lung cancer, although no studies have directly confirmed a direct interaction between KIF2C and CDK1/CCNB1, research has identified a significant positive correlation in their expression levels." (PMID 41333555, 2025). "The discovery of feedback loop mechanisms with cyclin dependent kinase 1 (CDK1) and wee1 like protein kinase (WEE1) or the discovery of microRNA (miRNA) target interactions in the development of lung cancer in non-smoking females, are examples of applications of systems biology." (PMID 29848999, 2018).
colorectal cancer (114 papers, 2008 to 2026). A primary or metastatic malignant neoplasm that affects the colon or rectum. "High level CDK1 pTyr15 was associated with prolonged disease-free survival for stage II colorectal cancer patients (n = 79)." (PMID 27383761, 2016). "Similarly, the expression of the gene encoding CDK1 is increased in tumor samples from patients with colorectal cancer compared to healthy controls, and the overexpression of CDK1 is associated with decreased overall survival of patients with colorectal cancer." (PMID 38277448, 2024). "For example, in colorectal cancer cells, abnormally elevated cdk1 activity promotes chromosomal lagging and bridge formation by accelerating microtubule polymerization." (PMID 40868871, 2025). "Consistently, phosphorylation of T33 and T317 by Cdk1 was shown to positively influence Sam68 cytoplasmic distribution and pro-oncogenic functions in colorectal cancer cells." (PMID 37792222, 2024). "Both genetic and pharmacological interventions targeting CDK1 have been shown to re-establish oxaliplatin sensitivity in colorectal cancer cells." (PMID 38844964, 2024). "For instance, resistance to oxaliplatin in advanced colorectal cancer cases has been attributed to elevated expression of cyclin-dependent kinase 1 (CDK1), spurred by deletions in N6-methyladenosine modification." (PMID 38844964, 2024). "CDK1 has been demonstrated to promote the proliferation, anti-apoptotic escape, as well as enhanced invasiveness and metastatic capacity of colorectal cancer cells." (PMID 37370088, 2023). "CDK4 is found to be amplified in colorectal cancer cells compared to normal cells, and evidence has shown that inhibiting certain CDKs such as CDK1, 2, 4/6, and 9 is useful in enhancing colorectal cancer cell (HCT-116) death." (PMID 37233465, 2023). "CDK1 inhibitors have been shown to stop the proliferation of colorectal cancer cells in in vitro and in vivo models." (PMID 38002302, 2023). "These high levels of CDK1 gene expression have been found to stimulate the proliferation of colorectal cancer cells." (PMID 38002302, 2023). "Several studies and analyses have connected CDK1 to immune infiltration in lung adenocarcinoma, colorectal cancer, and hepatocellular carcinoma." (PMID 37915086, 2023). "We have observed a concurrent downregulation of ZNF880 and upregulation of CDK1 in colorectal cancer samples, suggesting a potential direct or indirect regulatory relationship between the two." (PMID 37370088, 2023). "Recently, it was reported that DPP3 interacts with CDK1 protein in the colorectal cancer cell line and that DPP3 knockdown decreases proliferation, causes G2 arrest, promotes apoptosis, and inhibits cell migration." (PMID 37762480, 2023). "Among the prognostic risk factors, SNRPA1 was reported to be highly expressed in colorectal cancer tissues and promoted cancer progression through the regulation of PIK3R1, VEGFC, MKI67, and CDK1." (PMID 36212157, 2022). "A previous study suggested that targeting the CDK1 has reduced apoptotic resistance in colorectal cancer." (PMID 35330393, 2022). "Inhibition of CDK1 has been shown to reverse Paclitaxel-induced resistance in ovarian cancer cells and 5-FU-induced resistance in colorectal cancer." (PMID 35681641, 2022). "High-CDK1-expression colorectal cancer patients had a poor clinical outcome, and inhibition of CDK1 enhances 5-fluorouracil sensitivity in colorectal cancer." (PMID 35906389, 2022). "In colorectal cancer, high levels of miR-378a-5p reduces tumor burden through decreasing expression of CDK1." (PMID 36266723, 2022). "Previous studies have demonstrated that the expression levels of CDK1/4 are upregulated in poorly-differentiated colorectal cancer cells." (PMID 35814446, 2022).